EML4 (EMAP like 4)
Diseases named in the same sentence as EML4 in open-access papers (continued):
Sharing a sentence is not in itself a finding about the gene and the disease.
cancer (continued). "The resulting EML4-ALK fusion protein is constitutively active in these cancer cells and is a driver of tumorigenesis for these cells." (PMID 26517679, 2015). "EGFR, HER2, KRAS, PTEN and PI3K were sequenced for cancer-associated mutations; in addition, HER2 and EGFR copy numbers or EML4-ALK (echinoderm microtubule-associated protein-like 4–anaplastic lymphoma kinase) rearrangement were evaluated by FISH." (PMID 26247735, 2015). "We next evaluated the ability of the EML4-ALK-specific CTL clone to recognize the cancer cell line H2228, which expresses HLA-A*02:01 and EML4-ALK, using the IFN-γ ELISPOT assay." (PMID 24842630, 2014). "A tyrosine kinase inhibitor, crizotinib, has been shown to selectively inhibit growth of cancer cells with EML4-ALK fusion gene." (PMID 25360721, 2014). "A few reports have also identified EML4-ALK in other cancers, namely breast cancer and colorectal cancer." (PMID 24842630, 2014). "In other words, the aberrant activity of ALK tyrosine kinase induced by EML4-ALK translocation results in less-differentiated carcinomas, more dangerous and aggressive types of cancers." (PMID 25407901, 2014). "All carcinomas except one are less-differentiated, including 4 poorly and 3 moderately differentiated cases, suggesting that EML4-ALK rearrangements usually occurred in less-differentiated carcinomas." (PMID 25407901, 2014). "In that report, the differentiation levels were determined in 11 EML4-ALK positive carcinomas, which were identified by the same group previously." (PMID 25407901, 2014). "We have found that ALK TK mRNA level (normalized to house gene ABL) in the EML4-ALK-positive carcinomas is significantly higher (p < 0.0001 by Mann–Whitney test) than in the EML4-ALK-negative samples." (PMID 25407901, 2014). "In our study, comparison of EML4-ALK fusion status with the presence of EGFR and KRAS mutations in the same cancer samples revealed that EML4-ALK fusions occurred in the absence of EGFR or KRAS mutations." (PMID 23341890, 2013). "Some younger men have an echinoderm microtubule-associated protein-like 4 (EML4) and anaplastic lymphoma kinase (ALK) translocation (EML4-ALK), which causes their cancer." (PMID 22899945, 2012). "Previous investigations have shown that translocation of ALK can result in fusion with the neighbouring gene, EML4, in cancer cells." (PMID 20624322, 2010). "While EML4-ALK has a driving role in activating downstream signalling cascades such as RAS/MAPK, PI3K/AKT and JAK/STAT3 in EML4-ALK-rearranged cancers, other proteins also feedback into those signalling pathways and might contribute to disease progression." (PMID 39695132, 2024). "Consequently, there is a clear need to better understand the mechanisms involved in EML4–ALK-driven cancers so that new therapies can be developed that are capable of overcoming this resistance." (PMID 38458397, 2024). "As well as providing mechanistic insights on how EML4–ALK V3 alters cellular properties, these data raise the prospect that Eg5 inhibitors may be valuable alternative treatments for patients with EML4–ALK V3–driven cancers." (PMID 38458397, 2024). "Future work could explore in depth the functional role of the PTPN11 phosphorylated residues (Y62, Y542 and Y580) in signalling activation, drug resistance and cancer immunity in the EML4-ALK + NSCLC." (PMID 39695132, 2024). "EML4-ALK drives cancer primarily through sustained RAS/ERK signaling." (PMID 39488530, 2024). "Similarly, a significant reduction in cell viability was observed in an A3B-knockout (KO) EML4-ALK cancer cell line (H3122) treated with the Food and Drug Administration-approved ALK TKI alectinib." (PMID 38049664, 2024). "IHC of the in LUAD‐OG1 organoids showed ALK was over‐expressed, and the presence of EML4‐ALK fusion variant 1 was further validated by RT‐PCR and sanger sequencing using specific fusion primers, consistent with the genotype of the parental cancer." (PMID 36709476, 2023).
cancer (continued). "The response rates to fusions have been shown to be drastic for different cancers and may also depend on the fusion partners (in this case, EML4-ALK is the classic NSCLC reported translocation)." (PMID 37041305, 2023). "This high diversity level of the EML4-ALK fusion might confer cancer cells additional selective advantages." (PMID 37741817, 2023). "In addition, EML4-ALK (one of the fusion genes in cancer) can also be detected in the plasma samples from NSCLC patients." (PMID 36249712, 2022). "To further evaluate whether EML4-ALK associates with lipid membranes, we performed subcellular fractionation in patient-derived cancer cell lines expressing endogenous EML4-ALK." (PMID 33848463, 2021). "Furthermore, inhibition of EML4-ALK with crizotinib in H3122 patient-derived cancer cells suppressed not only wild-type RAS-GTP levels, but also the levels of GTP-bound, cytosolic KRAS-C185S." (PMID 33848463, 2021). "However, cancers harbouring EML4‐ALK V3 tend to respond less well to ALK inhibitors compared with cancers driven by EML4‐ALK V1." (PMID 34661367, 2021). "Although this cancer is linked to genetic instability, the DNA mutations targeted for adenocarcinoma therapy, including EGFR mutations and echinoderm microtubule-associated protein-like 4 (EML4)-anaplastic lymphoma kinase (ALK) translocations, are essentially absent in LSCC." (PMID 33799513, 2021). "EML4-ALK fusions identified in actual cancer cell–derived RNA-Seq data (BioProject ID PRJNA350335)." (PMID 32470133, 2020). "Besides these limitations, EML4-ALK rearrangement has been detected in CTCs from peripheral blood of NSCLC cancer patients." (PMID 37362555, 2020). "To test these hypotheses, we investigated the effects of ALK fusion protein monomerization in vitro and in vivo, and cc peptide treatment for the EML4-ALK-positive cells in cultured Ba/F3 and EML4-ALK-positive cancer cell lines." (PMID 32300555, 2020). "Such peptide therapies may provide a new therapeutic strategy for EML4-ALK cancers that are resistant to TKI." (PMID 32300555, 2020). "We searched for mutations in 22 cancer-related genes, using target sequencing techniques to further characterize the 12 patients who had AXL 3+ expression, of whom 6 had mutations in EGFR, 2 in KRAS, and 1 EML4–ALK fusion gene." (PMID 27100677, 2016). "Taken together, our findings show that CSC drugs targeting stem-like traits of cancer cells could be effective in controlling refractory EML4-ALK+ NSCLC." (PMID 26517679, 2015). "This is a new epitope-based vaccine therapy design for EML4-ALK-positive cancer cells." (PMID 24842630, 2014). "We next examined the differentiation levels of carcinomas in EML4-ALK positive carcinomas." (PMID 25407901, 2014). "EML4-ALK translocation is associated with early-onset and less-differentiated carcinomas." (PMID 25407901, 2014). "Interestingly, EML4-ALK fusion genes are more frequently found in younger patients and associated with less-differentiated carcinomas." (PMID 25407901, 2014). "The clinical features of EML4-ALK–positive carcinomas were also determined." (PMID 25407901, 2014). "Thus, if any metastasis or relapse occurs in the future in this patient, it is more likely that the relapse derives from EML4-ALK-positive cancer of the right lung." (PMID 23617234, 2013). "For the pathological analysis, cribriform structure, presence of mucous cells, extracellular mucus, and lack of significant nuclear pleomorphism, could all be seen in the EML4-ALK rearranged cancer, which was similar to findings in a previous report." (PMID 23341890, 2013). "As the existence of LLPS foci, such as FUS, which are formed by phase separation, is implicated in neurodegenerative diseases, the presence of similar compartments in cancers, such as EML4‐ALK+ NSCLC, could also contribute to the progression and aggressiveness of the disease." (PMID 34661367, 2021).
cancer (continued). "To date, only about two‐thirds of the kinome has been covered, and more substantial inferences could be made with further population of resources (such as PhosphoSitePlus), especially when the latter also cover cancer‐associated aberrations such as fusion gene products BCR‐ABL and EML4‐ALK." (PMID 30979792, 2019). "Similarly, we propose that treatment with stemness-targeting agent rapamycin could sensitize EML4-ALK+ NSCLC cells to conventional cancer drugs including ALK inhibitors." (PMID 26517679, 2015). "Indeed, cancer cells where genomic alterations of ALK lead to expression of truncated variants, such as NSCLC (EML4-ALK) and ALCL (NPM-ALK), are addicted to ALK signalling because translocations provide dimerization domains that render fusion proteins ligand independent." (PMID 26147305, 2015). "Thus, it is possible that the differentiation of carcinomas, regardless of smoking history, is associated with the expression of EML4-ALK mutant genes." (PMID 25407901, 2014). "This contrasts with NSCLC, where EML4-ALK (5%-7%) drives targeted therapy success, or TRK fusion-positive cancers, where NTRK inhibitors achieve high response rates." (PMID 41589214, 2026). "Unlike other recurrent gene fusions, such as EWS-FLI1, BCR-ABL, and EML4-ALK, which are preferentially enriched in specific cancer subtypes, PVT1 gene fusions occurred across cancer types." (PMID 40027648, 2025). "In the context of TKIs, this approach has thus far only been studied in cancer types that are addicted to mutant oncogenic kinases such as BCR-ABL, EML4-ALK and mutant EGFR19,22,23." (PMID 40781553, 2025). "In the context of cancer, studies evaluating kinase inhibitor collateral sensitivities have to date been restricted to drugs that block the oncogenes BCR-ABL, EML4-ALK and mutant EGFR19,22,23." (PMID 40781553, 2025). "In untreated cancer cells, EGR1 levels remained low despite high ERK signaling from EML4-ALK, consistent with EGR1 adaptation to tonic ERK signals." (PMID 39488530, 2024). "Here, we investigate the kinase responses in EML4-ALK V1 and V3-harbouring NSCLC cancer cells after acute inhibition with ALK TKI, lorlatinib (LOR)." (PMID 39695132, 2024). "For gene fusion, Pan Cancer 6 Fusion standard that had six types of fusions: TPM3-NTRK1, QKI-NTRK2, ETV6-NTRK3, EML4-ALK, CCDC6-RET, and SLC34A2-ROS1 was used." (PMID 38404964, 2024). "The EML4-ALK fusion protein acts as an oncogenic driver, promoting the development and progression of cancer cells." (PMID 38306516, 2024). "Changes in down-regulated genes were ETV4 (ETS Variant Transcription Factor 4) and ETV5 (ETS Variant Transcription Factor 5) are related to transcriptional regulation, EML4 (EMAP like 4), BCL2 and Myc are related to cancer development." (PMID 39834948, 2024). "Thus, inhibiting EML4-ALK fusion protein in cancer cells might decrease coagulability." (PMID 37940761, 2024). "How ALK activity impacts on EML4-ALK variant protein levels is unclear, although interactions with proteins such as the HSP90 chaperone that is critical for protecting proteins from degradation as well as maintaining the activity and stability of oncoproteins in cancers may be of importance." (PMID 38264745, 2023). "First, we confirmed that EML4-ALK localized to punctate structures in the cytoplasm, and not to the PM, by immunofluorescence (IF) in patient-derived cancer cells (H3122) that endogenously express this EML4-ALK variant." (PMID 33848463, 2021). "Using cell viability assays, we confirmed the potent activity against EML4-ALK fusion gene (WT, v1, and v3)-positive NSCLC cells (H3122 and H2228 cells) and patient-derived primary cancer cells (JFCR-028-3 and JFCR-018-1)." (PMID 33627640, 2021).
cancer (continued). "Almost all the fusion transcripts reported in KuNG FU are specific for a single cancer type, however three fusions (BRD4-NUTM1, CCDC6-RET and EML4-ALK) were found across a variety of different cancer types." (PMID 33257674, 2020). "To shed light on the specificity of these compounds towards EML4‐ALK cells, we analysed RNA‐seq expression data from the cancer cell line encyclopaedia (CCLE)." (PMID 32558295, 2020). "To further clarify the significance of SMYD2‐mediated methylation on EML4‐ALK protein on the growth of cancer cells, we examined the effect of exogenous introduction of lysine‐substituted EML4‐ALK proteins into two NSCLC cells with EML4‐ALK." (PMID 28370702, 2017). "Many cancer cells addicted oncogenes such as mutant EGFR, amplified HER2 and fused EML4-ALK rely on Hsp90 for their conformational maturation." (PMID 26097875, 2015). "Therefore, these receptor ligands may modulate various cancer phenotypes of EML4-ALK NSCLC cells." (PMID 24952482, 2014). "The EML4-ALK fusion gene was first described in 2007 by Soda and colleagues, who screened a cDNA library derived from the cancer tissue of a 62-year-old Japanese male patient with NSCLC." (PMID 25360721, 2014). "Since several growth factors can be simultaneously produced in cancer microenvironments, it is possible that HGF and EGFR ligands are co-expressed in EML4-ALK NSCLC cells." (PMID 24952482, 2014). "Since ALK (EML4-ALK) and SRC play a role in other cancers, this approach may have broader relevance." (PMID 41154443, 2025). "In cancers driven by mutant oncogenes, such as KIT or PDGFRA mutant gastrointestinal stromal tumours and EGFR or EML4-ALK mutant lung cancers, sequential treatments with up to fourth-line kinase inhibitor therapy have achieved long-term disease control and improved patient outcomes." (PMID 40781553, 2025). "Therefore, CAR-T therapy for ALK positive cancers needs to take into account not only the ALK kinase, but also the extracellular structures expressed by more important ALK fusion partners such as EML4 or NPM, among others." (PMID 36591504, 2022). "EML4-ALK is a chimeric receptor tyrosine kinase, hyperactivation of which drives cancer." (PMID 36483537, 2022). "Interestingly, we observed statistical significance for the loss of internal degrons from several fusion genes, such as 5′ EML4 fusions, 3′ NSD1 fusions and the previously validated 3′ ETV4 fusions, only when considered in conjunction with cancer type." (PMID 34795215, 2021). "Among these cancers, ALK gene fusions were identified to be most common in ALCL (60% cases, mainly NPM-ALK fusion), followed by IMT (~50% cases, mainly TPM3/4-ALK fusion), NSCLC (~5–7% cases, mainly EML4-ALK fusion), and other cancers." (PMID 32059449, 2020). "Expression of PD-L1 is induced via oncogenic signaling pathways, such as RAS/RAF/MEK/mitogen-activated protein kinase-ERK, phosphatidylinositol-3 kinase/phosphatase and tensin homolog/Akt/mammalian target of rapamycin, EGFR, and EML4-ALK pathways, in many cancer types." (PMID 33324391, 2020). "Consequently, we postulated that ALK kinase activity is dependent on EML4-ALK dimerization and that cc peptides would provide appreciable antiproliferative activities in ALK-rearranged cancers." (PMID 32300555, 2020). "In cancer cells with EML4-ALK, the transcription of the C-terminal region of ALK depends on the promoter activity of the fusion partner, EML4, which is a housekeeping gene for the stabilization of microtubules during mitosis, by which the C-terminal ALK protein level also becomes elevated." (PMID 30943926, 2019). "In particular, we validated a new event in EML4, a gene involved in cancer through a fusion with ALK that is not present in MDA-MB-231 cells." (PMID 29571299, 2018). "The identification of the EML4-ALK fusion in a subset of NSCLC patients, and the response of these patients to crizotinib is a clear example of the value of molecular genetics aligned with targeted approaches to cancer drug discovery." (PMID 26755435, 2016).
cancer (continued). "Thus, characterization of EML4-ALK fusion genes and clinical features of resulting carcinomas would be a great benefit to disease diagnosis and designing customized treatment plans." (PMID 25407901, 2014). "In this subset of NSCLC patients who are Chinese male never smokers, EML4-ALK translocation is associated with early-onset and less-differentiated carcinomas, which are likely caused by the aberrant expression of ALK mRNA and protein." (PMID 25407901, 2014). "Taken together, these results suggest that EML4-ALK translocation occurs more frequently in less-differentiated carcinomas with an early-onset in Chinese male never-smokers with NSCLC." (PMID 25407901, 2014). "By this method, we detected EML4-ALK translocation in 8 carcinomas, accounting for 8.42% in 95 Chinese male never-smokers with NSCLC." (PMID 25407901, 2014). "We have identified EML4-ALK fusion genes in 8 out of 95 carcinoma cases, accounting for 8.42% in Chinese male never-smokers with NSCLC." (PMID 25407901, 2014). "Thus, suppression of EGFR signaling is a shared property of EML4-ALK(V1)+ cancer cells and depends on oncogene activity, but is not a general property of oncogenic ALK receptor activity." (PMID 39488530, 2024). "EML4-ALK gene fusion is initiated by inversion in the short arm of chromosome 2, which juxtaposes the N-terminal of the EML4 promoter and the kinase domain of the ALK gene, ultimately leading to ligand-independent constitutive activation of ALK and promoting cancer cell proliferation and survival." (PMID 34054126, 2021). "Finally, by combining RNA-seq, single-molecule RNA FISH, and DNA FISH, we detected a cancer sample with EML4-ALK fusion RNA without forming the EML4-ALK fusion gene." (PMID 30718424, 2019). "Taking the EML4-ALK fusion protein as an example, we further summarized the sequence or structural features and the available experimental evidence to explain how this fusion gene might contribute to cancer carcinogenicity." (PMID 26347798, 2015). "Accumulating evidence indicates that ALK activity of EML4-ALK fusion protein mediates tumorigenicity of NSCLC cells via various oncogenic signaling pathways including PI3K/AKT signaling, which is a key regulator of stem-like properties in a cancer stem cell population." (PMID 26517679, 2015). "These 42 fusion transcripts included EML4-ALK and FRS2-NUP107 fusions, which were also reported from the 9,966 TCGA cancer samples, as well as 40 new fusion transcripts that were not previously documented." (PMID 30718424, 2019). "In addition, since EML4–ALK protein is only present in cancer cells and absent in normal cells, the TK inhibitors (TKIs) will be highly selective for cancer cells, thereby minimizing side effects of the treatment." (PMID 41213866, 2025). "A novel circular RNA F-circEA-2a mainly located in the cytoplasm generated by the EML4-ALK fusion gene was found, and although F-circEA-2a does not affect the proliferation of NSCLC cells, it can significantly affect the migration and invasion of cancer cells." (PMID 39464712, 2024). "Transfection of WT EML4‐ALK or K1451A‐, K1455A‐, or K1451A/K1455A‐subsituted EML4‐ALK showed a slight increase of phosphorylation levels of AKT at serine 473 and some tendency of growth promotion for both cancer cells (not statistically significant)." (PMID 28370702, 2017). "Interestingly, our study suggests that EML4-ALK rearrangements in Chinese male never-smokers with NSCLC are more frequently detected in younger patients and in less-differentiated carcinomas." (PMID 25407901, 2014).